ZNF804A (zinc finger protein 804A)
Diseases named in the same sentence as ZNF804A in open-access papers (continued):
Sharing a sentence is not in itself a finding about the gene and the disease.
schizophrenia (continued). "An additional link to schizophrenia is a frameshift variant in the GPATCH8 gene in exon 9 of transcript GPATCH8-201, an ortholog of ZNF804A, which has been shown to impact various mental illnesses via pre-mRNA processing." (PMID 36449109, 2023). "ZNF804A, XKR6, and IQCE genes have also been linked to other diseases, such as bipolar disorder, schizophrenia, memory loss, longevity, blood metabolite levels, asthma, and allergic rhinitis." (PMID 36233348, 2022). "Of note, ZNF804A which has been identified in multiple GWAS studies of schizophrenia, was one of the top differentially expressed genes (log2 fold change +1.26 corrected p < 3.32x10−19)." (PMID 35719055, 2022). "Systematic meta-analysis on the psychotic diseases including schizophrenia, BAD, and ADHD identified several gene variants in ZNF804A, the zinc finger DHHC-type-containing 8 (ZDHHC8) and the zinc finger with KRAB and SCAN domain 4 (ZKSCAN4) genes." (PMID 32117005, 2020). "ZNF804A, a zinc-finger protein, presents an odds ratio of 1.08 (0.92–1.26 95% CI) for schizophrenia samples." (PMID 32059228, 2020). "Data presented show the genotypic distribution of ZNF804A rs1344706 in 1265 patients with schizophrenia and 1051 healthy controls from the Russian population." (PMID 31193559, 2019). "Previous study have found that the association between several SNPs in ZNF804A, NRGN and schizophrenia were different across distinct ethic population, the significance level in Asian populations were not across the whole genome." (PMID 29599495, 2018). "In the present study, we aimed to provide further evidence for the implication of ZNF804A gene variation (i.e. rs7597593 and rs1344706) on psychosis proneness and explore, for the first time, whether sex was playing a role on this association as suggested by a previous study in schizophrenia." (PMID 28931092, 2017). "The Zinc finger protein 804A (ZNF804A) is a promising candidate gene for schizophrenia and the broader psychosis phenotype that emerged from genome-wide association studies." (PMID 28931092, 2017). "It is known or predicted to regulate hundreds of genes, whose targets include many schizophrenia susceptibility genes, such as BDNF, ZNF804A, TCF4 and CACNA1C37,38." (PMID 29118371, 2017). "One of the first genes that has achieved genome-wide level of statistical significance in schizophrenia GWAS is the Zinc finger protein 804A (ZNF804A)." (PMID 28931092, 2017). "This would be consistent with findings in relation to the ZNF804A gene in a sample with schizophrenia." (PMID 26114663, 2015). "But beyond these statistics, knowing the significance of the finding for understanding and treating schizophrenia requires several questions to be answered, including: what does ZNF804A do?" (PMID 25315827, 2015). "The transcriptional targets of zinc finger protein 804A (ZNF804A), a top schizophrenia candidate, were recently reported by our group from RNA-seq analysis in which the gene was knocked down in neurons derived from iPSCs." (PMID 26491539, 2015). "ZNF804A (Zinc Finger Protein 804A) has been identified as a candidate gene for schizophrenia (SZ), autism spectrum disorders (ASD), and bipolar disorder (BD) in replicated genome wide association studies (GWAS) and by copy number variation (CNV) analysis." (PMID 25905630, 2015). "Since developmental mechanisms are suggested in the pathophysiology for schizophrenia, expression of Zfp804A, the rat homolog of ZNF804A, was investigated in the developing rat brain." (PMID 26148198, 2015). "Here we studied the effects of schizophrenia risk genes MIR137, TCF4, and ZNF804A on macroscopic brain variation in healthy volunteers." (PMID 25217366, 2014). "In two accompanying papers, five schizophrenia susceptibility genes including CSMD1, C10orf26, CACNA1C, TCF4, and ZNF804A were validated as miR-137 targets, providing additional evidence for the involvement of miR-137 in schizophrenia." (PMID 25250332, 2014).
schizophrenia (continued). "ZNF804A acts as a transcription factor and regulates the transcription of genes related to schizophrenia." (PMID 24980144, 2014). "Recently, another human zinc finger protein ZNF804A gene, which also encodes a protein product with a C2H2-type domain like Zfp326, was reported to be associated with schizophrenia and a broader psychosis phenotype." (PMID 22666313, 2012). "Recently genome wide association studies (GWAs) lead to identification of new susceptibility genes with genome-wide levels of significance: zinc finger gene ZNF804A on chromosome 2q32 or the MHC-locus at 6p21 on schizophrenia." (PMID 21702894, 2011). "ZNF804A is the first gene to reach genome-wide significance for both schizophrenia and bipolar disorder, although the exact function of its protein products is currently unknown." (PMID 38702695, 2024). "The identified interaction between ZNF804A/ZFP804A and NT5C2 suggests a shared biological pathway pertinent to schizophrenia susceptibility within a neuronal cell type thought to be central to the neurobiology of the disorder, providing a better understanding of its genetic landscape." (PMID 38279611, 2024). "By selecting SNPs associated with the schizophrenia and infant right frontal lobe white matter volume in our cohort, we identified genes overrepresented for pathways involved in neuron development, many of which have previously been validated in schizophrenia models (e.g., ZNF804A, DISC1, NRXN3)." (PMID 37037832, 2023). "Despite the lack of association between ZNF804A rs1344706 and white matter integrity in schizophrenia, T allele carriers present higher white matter density in the left prefrontal lobe and bilateral hippocampi." (PMID 34566604, 2021). "The rs1344706 polymorphism in ZNF804A is robustly associated with schizophrenia and schizophrenia is, in turn, associated with abnormal non-rapid eye movement (NREM) sleep neurophysiology." (PMID 34329479, 2021). "Several genes were validated in APA sperm that were associated with autism spectrum disorder (CACNA1H, CNTNAP2, GRIN1, SHANK2, SHANK3, ZNF804A), schizophrenia (TCF3, ZNF804A), and bipolar disorder (COMT, DRD4, GRIN1, MBP, PRKCZ, SHANK2, TRPM2, ZNF804A), and in APA blastocysts (CACNA1H)." (PMID 32610362, 2020). "We show that ZNF804A is a nuclear protein that interacts with neuronal RNA splicing factors and RNA-binding proteins including RBFOX1, which is also associated with schizophrenia, CELF3/4, components of the ubiquitin-proteasome system and the ZNF804A paralog, GPATCH8." (PMID 30597088, 2019). "More recent evidences suggested that ZNF804A localizes to synapsis and that it plays a role in neurite formation, maintenance of dendritic spines, and activity-dependent structural plasticity, which are found to be altered in brains of schizophrenia patients." (PMID 28931092, 2017). "For example, SNP rs1344707 in ZNF804A is significantly associated with schizophrenia risk in European populations, however is not in a Chinese population." (PMID 27601205, 2016). "ZNF804A modulates hippocampal γ oscillations and, ultimately, the co-ordination of distributed networks belonging to the hippocampus and the prefrontal cortex, which are aspects known to be impaired in schizophrenia." (PMID 27601987, 2016). "In summary, ZNF804A illustrates that a statistically compelling genetic association to schizophrenia risk does not, in itself, lead to any immediate functional understanding nor therapeutic implications." (PMID 25315827, 2015). "Indeed, the PGC2 meta-analysis finds additional SNPs within ZNF804A which are also genome-wide significant (Schizophrenia Working Group of the Psychiatric Genomics Consortium, 2014)." (PMID 25315827, 2015). "DNA sequence variation in ZNF804A and TCF4 has been robustly associated with schizophrenia risk." (PMID 25217366, 2014).
schizophrenia (continued). "ZNF804A and TCF4 are believed to encode transcription factors, but little is known about the mechanistic pathways via which they might increase risk for schizophrenia." (PMID 25217366, 2014). "However, little is known about the biology of ZNF804A and its role in schizophrenia." (PMID 30597088, 2019). "In the future, ANK3-ZNF804A interaction analysis should be investigated in other psychiatric disorders, such as bipolar disorder and schizophrenia, which have been found to be highly correlated with the ANK3 or ZNF804A gene." (PMID 38702695, 2024). "In the results of schizophrenia, known schizophrenia genes like WBP1L (p = 2.24E-14), TMTC1 (p = 3.75E-14), ZNF804A (p = 8.50E-14), TAOK2 (4.82E-12) and so on showed significant association." (PMID 35004692, 2021). "This SNP maps near the pseudogene CACYBPP2, between the nucleoporin NUP35 and the zinc finger protein ZNF804A, a candidate for ASD, schizophrenia, and other neuropsychiatric disorders." (PMID 30134952, 2018). "Arguably this is already happening in schizophrenia where both the micro-RNA MIR137 and zinc finger protein ZNF804A genes appear to be involved in regulating the function of other genes." (PMID 22547958, 2011). "No enrichment was observed between any class of schizophrenia, ID-associated and control/sibling de novo mutations and differentially spliced or DEX genes in ZNF804A-depleted cells." (PMID 30597088, 2019). "In this study, we have shown that genetic variation in schizophrenia risk genes MIR137, TCF4, and ZNF804A does not lead to alterations in TBV, GM, WM, or hippocampal brain volumes as measured with structural MRI in healthy young adults." (PMID 25217366, 2014).
bipolar disorder (23 papers, 2011 to 2024). A disorder of the brain that causes unusual shifts in mood, energy, activity levels and the ability to carry out day-to-day tasks. "Genome-wide association studies have similarly identified an enduring genetic association between the ZNF804A risk-variant known to increase susceptibility for bipolar disorder and the phentotype for (ab)normal functional connectivity during theory of mind." (PMID 26834648, 2015). "In addition, genes linked to ID (TCF4, CPLX1, CDK6, KDM5B), ASD (RORA, KDM5B), and bipolar disorder (ZNF804A) were also among the 16 differentially expressed target genes." (PMID 29665782, 2018). "Comparison with other published GWA studies for bipolar disorder, excluding those with partial overlap of subjects, appears to corroborate several loci and candidate genes, including CNTNAP5, ZNF804A, ZNF659, SORCS2, and ZNF536." (PMID 24387768, 2014).
psychosis (23 papers, 2012 to 2022). "The authors suggested that ZNF804A was associated with a psychosis subtype in which cognition was relatively less impaired." (PMID 36293479, 2022). "Previous data from multiple populations have demonstrated that ZNF804A is a risk gene for the psychosis." (PMID 33303946, 2021). "An example of this is the Genetics and Psychosis (GAP) study, which looked at a purported association between a variant of the ZNF804A gene and poor outcomes after first-episode psychosis." (PMID 34559060, 2021). "According to the current knowledge of ZNF804A rs1344706, T allele carriers tend to be susceptible to psychosis." (PMID 35046850, 2021). "Our analysis also highlights genes identified via GWAS studies and implicated in psychosis (ZNF804A) and suicidal behavior (SKA2)." (PMID 31481758, 2019). "The single nucleotide polymorphism rs1344706 within the second intron of ZNF804A was the first to show genome-wide significant association for the broad psychosis phenotype." (PMID 27837918, 2017). "ZNF04A (zinc finger protein 804A) was originally identified as a schizophrenia risk gene but then found to be associated with a broader psychosis phenotype including BD." (PMID 26210959, 2016). "Another psychosis-related gene, the ZNF804A rs1344706, is also associated with prefrontal brain connectivity." (PMID 25628553, 2014). "Based on odds ratios, ZNF804A appears to act as a susceptibility site for psychosis although its contribution is likely very small." (PMID 23672587, 2013). "Despite this abundance of statistical evidence for an association of ZNF804A with psychosis, only modest effect sizes have been reported with odds ratios of around 1.10 (95% confidence interval 1.07–1.14), and its functional mechanisms are unclear." (PMID 22840435, 2012). "Three genes we observed to be regulated by ZNF804a expression are directly involved in dopaminergic transmission and cAMP signaling, two pathways thought to underlie many of the symptoms of psychosis." (PMID 22384243, 2012). "Seven psychosis-implicated SNPs across five different genes (proxies of ZNF804A-rs1344706, CACNA1C-rs1006737, BDNF-rs6265, DISC1-rs2793092, DISC1-rs11122319, NRG1-rs6994992 and NRG1-rs35753505 itself) were examined in our independent sample for effects on brain volume." (PMID 36168994, 2022). "According to the hypothesis of the psychosis continuum, we hypothesize that ZNF804A variability will be associated with the positive dimension of both traits." (PMID 28931092, 2017). "The rs1344706 psychosis risk allele (i.e., A) of ZNF804A has lower binding affinity for proteins in the cell nucleus, such as transcription factors and, potentially as a result of this, shows significantly increased expression compared to its counterpart (C allele) in healthy controls." (PMID 26966642, 2016). "Our results provide further support for the involvement of the GWA-discovered ZNF804A, in particular rs1344706 allele A, at least when in double-dose within a homozygous genotype, in inducing susceptibility to psychosis by demonstrating its effect in reducing FA in WM microstructure." (PMID 26966642, 2016). "Changes in hippocampal‐PFC co‐ordination, driven by differences in oscillatory activity, may be one mechanism by which ZNF804A impacts on brain function and risk for psychosis." (PMID 25757652, 2015). "Although ZNF804a is a relatively strong candidate susceptibility gene, the function of the protein and the molecular mechanism responsible for enhancing risk for psychosis remains unknown." (PMID 22384243, 2012). "The role of the SNP ZNF804A rs1344706 in the formation and progression of psychosis is still unclear." (PMID 35046850, 2021). "Additive interaction of the SNP rs1006737 CACNA1C with rs1344706 in the zinc finger protein 804A gene (ZNF804A) has been linked to defects in white matter microstructure and psychosis, although the effect of rs1344706 is thought to be larger than rs1006737." (PMID 31331039, 2019).
psychosis (continued). "In this sense, despite all the new studies with ZNF804A, the variability within this gene has been understudied in relation to psychosis proneness." (PMID 28931092, 2017). "Regarding the differences between males and females in relation to ZNF804A genetic variability, to the best of our knowledge, this is the first study exploring this in psychosis proneness." (PMID 28931092, 2017). "Also, a high degree/likelihood of replication was found for the two GWAS- (ZNF804A and CACNA1C) and one candidate-implicated (BDNF) SNPs, which supports their involvement in psychosis and brain structure." (PMID 36168994, 2022). "In our study, the predominantly female sample has allowed us to detect the ZNF804A by-sex effect in psychosis proneness, although the lower number of males included is a limitation that might have influenced our results." (PMID 28931092, 2017). "The ZNF804A influences the expression of three genes involved directly in dopaminergic transmission (i.e. DRD2 and COMT) and cAMP signalling (i.e. PDE4B), two pathways thought to underlie many of the symptoms of psychosis." (PMID 28931092, 2017). "The best-established psychosis risk allele (rs1344706), located in the third intron, influences ZNF804A mRNA in foetal but not adult human brain, with the risk allele being associated with lower expression." (PMID 26210959, 2016). "Although our data were obtained in healthy volunteers, ZNF804A‐related differences in hippocampal theta might become pathophysiological in the presence of other genetic and environmental insults, contributing to psychosis." (PMID 25757652, 2015). "Genetic imaging studies link the SZ risk variant rs1344706 on the ZNF804A gene to psychosis via alterations in functional brain connectivity during WM, but no work has looked at the effects of ZNF804A on WM with face-processing components." (PMID 23295962, 2013). "Only two previous studies have explored the implication of ZNF804A on psychosis-related (or attenuated) traits in non-clinical samples." (PMID 28931092, 2017). "Only two previous studies have explored the effect of the ZNF804A gene on psychosis proneness in non-clinical samples." (PMID 28931092, 2017).
autism spectrum disorder (7 papers, 2011 to 2021). A spectrum of developmental disorders that includes autism, and Asperger syndrome. "Copy number variants (CNVs) of ZNF804A have been observed in patients with autism spectrum disorders (ASDs), anxiety disorder, and BD, suggesting that ZNF804A is a dosage sensitive gene for brain development." (PMID 33446247, 2021).
cognitive deficit (4 papers, 2019 to 2022). "Such CNVs included a duplication overlapping ZNF804A detected in one Turkish AD patient; heterozygous deletions in a region overlapping this gene have been previously reported in 2 AD cases, 4 mild cognitive impairment (MCI) cases, and one control." (PMID 34321086, 2021).
alcohol withdrawal (2 papers, 2021 to 2024). "Since the development of alcohol withdrawal syndrome after abstinence is likely due to alcohol-induced neuronal damage in the brain, genes associated with brain neurons, such as ANK3 and ZNF804A, may have unknown mechanisms of action in alcohol withdrawal syndrome." (PMID 38702695, 2024).
Anxiety (2 papers, 2021 to 2024). Intense feelings of nervousness, tension, or panic often arise in response to interpersonal stresses. "Individuals carrying the ANK3 rs10994336 T allele and ZNF804A rs7525957 CC homozygote genotype had the highest anxiety and aggression scores." (PMID 38702695, 2024). "This study primarily focuses on exploring the single and interaction effects of single-nucleotide polymorphisms in the ANK3 and ZNF804A genes on anxiety and aggression severity manifested in AWS." (PMID 38702695, 2024). "Therefore, the moderating effect of ZNF804A rs7525957 on anxiety and aggression appears only in ANK3 rs10994336 T allele variation." (PMID 38702695, 2024). "Therefore, the objective of this study was to examine the effects of ANK3 and ZNF804A variants, as well as their interaction, on the anxiety and aggression severity of AWS in patients diagnosed with AUD." (PMID 38702695, 2024). "The interaction of ANK3 and ZNF804A accounted for a significant portion of the variance in anxiety (β = -0.20, t = -2.25, p = 0.025) and aggression (|β|s > 0.23, |t|s > 2.59, p < 0.010)." (PMID 38702695, 2024). "ANK3, ZNF804A, and the interaction term ANK3 x ZNF804A were entered as predictors of anxiety and aggression." (PMID 38702695, 2024). "Specifically, in ZNF804A rs7525957 CC homozygote carriers, ANK3 rs10994336 T allele carriers (M = 31.84, SD = 9.57) exhibit higher anxiety than CC homozygote carriers (M = 35.72, SD = 10.14) (t = 2.72, p = 0.007)." (PMID 38702695, 2024). "Lastly, a series of hierarchical regression analyses was conducted to confirm the interaction effects of ANK3 and ZNF804A on anxiety and aggression." (PMID 38702695, 2024). "Interestingly, Steinberg and colleagues identified two ZNF804A deletions from a Scottish patient with SZ and an Icelandic patient with anxiety, and one ZNF804A duplication in an Icelandic patient with BD." (PMID 33446247, 2021). "However, MANOVA and a series of interaction analyses revealed that ZNF804A rs7597593 could regulate the effect of ANK3 rs10994336 on AWS-related mood and behavior, including anxiety, physical and verbal aggression, anger, and hostility." (PMID 38702695, 2024).